SIRT1 (sirtuin 1)
Diseases named in the same sentence as SIRT1 in open-access papers (continued):
Sharing a sentence is not in itself a finding about the gene and the disease.
tumor (continued). "The function of SIRT1 in the EMT process is associated with tumour types." (PMID 34395273, 2021). "Furthermore, the partial restoration of ciliary expression in CCA cells by inhibition of either HDAC6 or SIRT1 has been linked to decreased cell growth and migration in the tumor cells." (PMID 35096835, 2021). "Taken together, these results suggest that SIRT1 overexpression is associated with ActD resistance, and that inhibiting SIRT1 with Rp1 could be of therapeutic benefit to overcome drug resistance in tumor cells." (PMID 32151067, 2020). "High SIRT1 levels are associated with tumor progression and prognostic prediction in GC patients." (PMID 31689236, 2019). "A possible explanation for this finding is that the changes of the ADC (ΔADC) are associated with the tissue cellularity/cellular density, while the levels of SIRT1 directly associated with chemoradiation resistance of tumour cells, also reflect the situation of cellularity/cellular density." (PMID 31684999, 2019). "Interestingly SIRT1 also has been implicated in lipid metabolism regulation under tumour nutrient deprivation." (PMID 30356832, 2018). "Considering that SIRT1 and/or PGC-1α expression is highly associated with tumor invasion and metastasis, the SIRT1/PGC-1α axis may provide an important molecular link that couples lipid metabolism to tumor malignant progression." (PMID 30242145, 2018). "It is reported that SIRT1 is associated with tumor metastasis in several kinds of tumors." (PMID 28112277, 2017). "The condition and activity of Sirt1 protein in tumor cells may therefore probably play a role to cause the cell response to epigenetic stress and treatment." (PMID 26959057, 2016). "We also analyzed the mechanisms underlying the regulatory effect of MSCs-Sirt1 on PCa tumor growth." (PMID 27764779, 2016). "Also, nuclear SIRT1 expression has been associated with advanced tumor invasion, high pathological T stage and lymph node metastasis in NSCLC." (PMID 25915617, 2015). "In non-tumor specimens, the association of SIRT1 with Notch was discussed about stem cell self-renewal, asymmetric cell division, stem cell aging, differentiation of neural precursor cells, bicuspid aortic valve pathogenesis, and vascular growth and energy homeostasis." (PMID 25420528, 2014). "Additionally, studies involving the influence of SIRT1 deficiency on in vivo tumorigenesis have shown that SIRT1 deficiency confined to the intestines led to reduced polyp and tumor formation." (PMID 24897117, 2014). "Additionally, tumors from SIRT1-deficient mice exhibited significantly increased apoptotic rates, without affecting their proliferation, indicating that SIRT1 promotes survival of tumor cells." (PMID 23799088, 2013). "As previously suggested by others, in this study we also find that inhibition of SIRT1 may be an effective strategy for the prevention of tumor development in high-risk patients or as a therapeutic strategy in established tumors." (PMID 23024800, 2012).
tumor (continued). "Accordingly, the effect of SIRT1 may vary according to the cell type, stage of tumor development, and accompanying mutation status of tumor related genes." (PMID 23024800, 2012). "Also, the overexpression of cytoplasmic SIRT1 was associated with a larger tumor size in H2BC, which might indicate the ability of SIRT1 to regulate biological behaviors, including colony formation and cell cycle progression in BC cells." (PMID 39858444, 2025). "Therefore, analyzing the association between SIRT1 variants and tumor location may help clarify their potential site-specific contribution to colorectal carcinogenesis." (PMID 40507674, 2025). "Therefore, CCL3/VIRMA/SIRT1 axis may be one of the important mechanisms underlying tumor evolution and metastasis and is a potential new therapeutic target for ICC." (PMID 36691046, 2023). "In vitro and in vivo experiments using SIRT1 inhibitors showed a reduction in tumor growth associated with enhanced ciliary expression, suggesting that the reestablishment of PCs in CCA cells by means of SIRT1 inhibitors may be a potential therapeutic approach." (PMID 37510333, 2023). "The main function of SIRT1 is to deacetylate certain proteins that play a key role in gene expression, thereby regulating its downstream-related signaling pathways and accelerating the cell cycle, reducing apoptosis, and causing rapid proliferation of tumor cells." (PMID 33345272, 2021). "However, whether SIRT1 is pro- or anti-tumour growth, particularly its involvement in CCA associated with USP22, remains unknown." (PMID 34226501, 2021). "Thus, while SIRT1 may play an important role in preventing tumor formation, the role of SIRT1 and its splice variant in senescence and apoptosis remains to be better understood." (PMID 28703423, 2017). "Furthermore, the effect of SIRT1 may vary according to the accompanying mutation status of SIRT1 gene or other tumor-related genes or due to differences in downstream targets of the enzyme." (PMID 26999517, 2016). "Due to the fact that SIRT1 activity regulates the function of signaling pathways associated with cell growth and motility, its overexpression could have grave consequences for tumor progression." (PMID 25569080, 2015). "Thus, the effect of SIRT1 may vary according to the cell type, stage of tumor development, and accompanying mutation status of tumor related genes." (PMID 24223900, 2013). "Since sirtuin 1 inhibits the mTOR pathway, we speculated whether H2A.Z downregulation due to sirtuin 1 overexpression might be mediated by repression of mTOR pathway, which is overactive and associated with tumor progression in PCa." (PMID 24127549, 2013). "Conversely, SIRT1 can exert a tumor suppressive role in K‐RAS‐driven NSCLC by modulating cell apoptosis and extracellular matrix organization." (PMID 40855785, 2026). "In oncology, SIRT1 exhibits context-dependent roles, functioning either as a tumor suppressor by maintaining genomic stability or as a tumor promoter by enabling cancer cell survival under stress." (PMID 41601525, 2026). "In NSCLC, SIRT1 exhibits dual roles, acting as both an oncogenic driver and anti‐tumor factor depending on the context." (PMID 40855785, 2026). "Cambinol was first identified as a SIRT1/2 inhibitor (IC50 ≈ 50–60 μM) with anti-tumor activity in preclinical lymphoma and carcinoma models." (PMID 41300302, 2025).
tumor (continued). "These subtype-specific patterns suggest that SIRT1 supports tumor progression through distinct molecular axes depending on the underlying redox and genetic landscape, warranting tailored therapeutic approaches for each histological subtype." (PMID 41008982, 2025). "SIRT1 is involved in DNA damage repair and contributes to genomic stability, thereby influencing tumor cell proliferation." (PMID 41011152, 2025). "We showed that the pharmacological inhibition of SIRT1 using EX527 reduced tumor growth in vivo and lowered nuclear PD‐L1 levels, thereby enhancing the antitumor immune response." (PMID 39988985, 2025). "Downregulated in CRC, SIRT1’s expression gradually decreases with tumor progression, showing a strong correlation with overall survival in CRC patients." (PMID 40229278, 2025). "Conversely, although the upregulation of SIRT1 can promote tumor growth, SIRT1 also plays a role in maintaining the stability of genetic material by reducing DNA damage, especially in aging cells." (PMID 40052151, 2025). "Selisistat enhances paclitaxel efficacy through synergistic anti-tumor effects via SIRT1 inhibition." (PMID 41425553, 2025). "The apparently contradictory effects of SIRT1 in NSCLC reflect context-specific routing through HNRNPD/PGC-1α-driven pro-angiogenic versus FOXO1-dependent tumor-suppressive networks." (PMID 41425553, 2025). "Among these, SIRT1, SIRT4, and SIRT5 are the most highly implicated regulators, exhibiting both tumor-suppressive and tumor-supportive functions, depending on the cellular and tumor context." (PMID 41425553, 2025). "Future studies should elucidate how SIRT1-mediated redox regulation contributes to therapeutic resistance, tumor progression, and immune evasion in each molecular subtype, particularly in aggressive forms, such as HER2-positive and TNBCs." (PMID 41008982, 2025). "Adoptive transfer of neutrophils with inhibited NAMPT or SIRT1 decreased tumor angiogenesis and growth in murine models." (PMID 40050933, 2025). "In these malignancies, the SIRT1–FOXO axis influences tumor cell survival, proliferation, apoptosis, and chemoresistance, depending on the balance between tumor-suppressive and pro-survival signaling." (PMID 41300302, 2025). "In Type I EC, SIRT1 is influenced by estrogen signaling and plays a dual role in regulating tumor suppression and progression." (PMID 41300302, 2025). "Histological analyses validated these imaging results, revealing heterogeneous upregulation of SIRT1 in the tumor parenchyma, particularly in hypoxic and peri-necrotic regions." (PMID 40710366, 2025). "SIRT1 functions as an oncogene as well as a tumor suppressor, regulating cell cycle progression, apoptosis, cell senescence, and oxidative stress resistance." (PMID 40664665, 2025). "SIRT1 is overexpressed in ER-positive breast cancer and was shown to promote tumor progression by facilitating ER and estrogen-related receptor signaling." (PMID 40165290, 2025). "The experimental results indicated a significant inhibition of tumor progression in the Sirt1‐KO group." (PMID 39783838, 2025). "In animal study, Sirt1 overexpression downregulated enzymes involved in androgen synthesis, exerting a significant anti-tumor effect." (PMID 40075208, 2025). "Overexpression of Sirt1 suppressed androgen secretion in tumor cells and inhibited tumor progression." (PMID 40075208, 2025). "Overexpressing Sirt1 significantly lowers brain androgen levels and delays tumor progression in mouse models." (PMID 40075208, 2025). "Their finding indicated that SIRT1 takes part in tumor formation by repressing genotoxic stress-induced apoptosis." (PMID 39858444, 2025). "For instance, SIRT1, an NAD+-dependent histone deacetylase belonging to the sirtuin family, has been closely associated with tumor development." (PMID 39944690, 2025).
tumor (continued). "The seven mammalian sirtuins (SIRT1–7) have diverse functions based on their cellular context, subcellular localization, and tumor subtype, positioning them as potential biomarkers and therapeutic targets." (PMID 41471349, 2025). "Due to SIRT1’s ability to modify the activity of proteins essential for carcinogenesis, it promotes both drug resistance and tumor growth and progression." (PMID 40439888, 2025). "Collectively, these studies support the tumor-promoting role of SIRT1 in HCC through mitochondrial redox control and stress adaptation." (PMID 41008982, 2025). "In vivo studies further showed USP22 overexpression significantly increased subcutaneous tumor growth and pulmonary metastases in nude mice, effects abrogated by SIRT1 knockout." (PMID 41301681, 2025). "Given its role in promoting tumor survival and progression, SIRT1 is being explored as a potential therapeutic target." (PMID 41300302, 2025). "Sirt1 is involved in many biological processes such as drug resistance, energy metabolism, cell proliferation, tumour development, autophagy and apoptosis." (PMID 40837398, 2025). "SIRT1 is the most prominent member of the deacetylase family, and the enhanced anti-tumor properties of Th1/17 cells rely on the enhanced activity of the NAD-dependent enzyme SIRT1." (PMID 40529366, 2025). "Given its involvement in tumor progression, chemoresistance, and immune evasion, SIRT1 represents a promising therapeutic target." (PMID 41300302, 2025). "Similar to our results, the findings in the previous study demonstrated that SIRT1 was overexpressed in OS and promotes tumor growth, invasion, and chemoresistance." (PMID 40026531, 2025). "In vivo, experiments were conducted using a subcutaneous U14‐luc tumor model in C57BL/6 mice to examine the effects of SIRT1 on PD‐L1 expression and nuclear localization." (PMID 39988985, 2025). "SIRT1 promotes Dox resistance, tumor growth, angiogenesis, and metastasis via redox dysregulation; inhibiting SIRT1 or GSH reverses these effects." (PMID 41425553, 2025). "Sirtinol administration was shown to effectively slow down or temporarily halt tumor growth in a senescence-like growth arrest via the inhibition of SIRT1 function in human lung and breast cancer lines." (PMID 41333420, 2025). "RNA sequencing, RT-qPCR and Western blotting were performed to assess the expression levels of steroid enzymes, tumor drug resistance, Sirt1, FOXO1genes and proteins." (PMID 40075208, 2025). "By deacetylating transcription factors including Snail and Slug, SIRT1 promotes the transition from an epithelial to a mesenchymal phenotype, thereby facilitating tumor cell invasion and metastasis." (PMID 41300302, 2025). "Elevated SIRT1 expression has been correlated with poor prognosis, aggressive tumor behavior, and resistance to chemotherapy." (PMID 41300302, 2025). "SIRT1 suppression also enhances the Beclin1–Rubicon interaction, which inhibits autophagy in tumor cells." (PMID 40298803, 2025). "As the oncogenes of CRC, both nuclear enriched abundant transcript 1 (NEAT1) and Pseudouridine synthase 7 (PUS7) are involved in the initiation of the tumor through SIRT1/Wnt/β-catenin axis in the nude mice model." (PMID 40567502, 2025). "SIRT1 induces G1 phase arrest through the NF-κB/Cyclin D1 signaling pathway, thereby inhibiting tumor proliferation." (PMID 40567502, 2025). "At this point, SIRT1 exhibited tumor suppressor property; due to the limitation of study cases, the mechanisms need to be further clarified." (PMID 41300302, 2025). "These interactions suggest that SIRT1 can either promote or suppress tumor development, depending on the context." (PMID 40052151, 2025).
tumor (continued). "On the other hand, SIRT1 overexpression induced tumour growth and cisplatin resistance in nude mice." (PMID 39935420, 2025). "In vitro, glucose deprivation caused activation of SIRT1 and stabilization of HIF-2α in SW1353 and JJ012 cells, increasing tumor cell survival compared to SIRT1-silenced cells." (PMID 40004005, 2025). "In contrast to the tumor-promoting effects of SIRT1 in GC, the mechanisms by which SIRT1 exerts its inhibitory effects on GC are remarkably diverse." (PMID 40567502, 2025). "In other words, SIRT1 contributes to the suppressive character of these cells, and when it is diminished, the balance flips back to anti-tumor immunity." (PMID 41425553, 2025). "Since Type II EC often lacks estrogen receptor expression, SIRT1 functions independently of estrogen signaling and contributes to tumor progression through alternative mechanisms, such as DNA repair and chemoresistance." (PMID 41300302, 2025). "In vivo, 1-P significantly inhibited tumor growth in mice, but SIRT1 overexpression diminished this effect (p < 0.05)." (PMID 40872615, 2025). "SIRT1’s functional impact appears highly dependent on its subcellular localization and the tumor’s molecular subtype." (PMID 41471349, 2025). "This is why NF-κB is a target for many anti-tumor drugs, which generally work by increasing the expression and activity of SIRT1." (PMID 40567502, 2025). "Circular RNA 0005075 promotes GBM progression by inhibiting Sirt1, suggesting a potential tumor-suppressive role for Sirt1." (PMID 40450300, 2025). "Conversely, SIRT1 acts as a tumor promoter by inhibiting the activity of oncosuppressors through their deacetylation." (PMID 39215785, 2025). "In some pathophysiological conditions, including tumor progression, SIRT1 seemed to activate protective signaling pathways controlled by AKT (serine/threonine-specific protein kinases) and PDK1 (phosphoinositide-dependent protein kinase 1)." (PMID 40507674, 2025). "MGM presented highly focused SIRT1‐high subclusters that topographically overlapped with fibroblast‐like and mesenchymal ECM regions, suggesting site‐specific upregulation within tumor‐associated stromal niches." (PMID 41208649, 2025). "We subsequently evaluated the impact of alterations in SIRT1 expression levels within tumor cells on tumor immunity." (PMID 39783838, 2025). "Some studies have observed higher SIRT1 expression in EC tissues compared to normal endometrial tissues, suggesting a role in tumor progression." (PMID 41300302, 2025). "Kaempferol activates SIRT1 and induces apoptosis, suppresses inflammation, and inhibits tumor cell migration." (PMID 41304967, 2025). "SIRT1, SIRT2, and SIRT7 have been implicated in the development and metastasis of EC, while SIRT6 has been shown to exhibit anti-tumor properties in this context." (PMID 41471349, 2025). "Like CRC, the SIRT1 inhibitor Tenovin-6 also exerts anti-tumor effects in GC through the same mechanism." (PMID 40567502, 2025). "Given its central role in oxidative stress adaptation and therapeutic resistance, the pharmacological inhibition of SIRT1 has emerged as a promising approach to disrupt tumor survival mechanisms and enhance the efficacy of existing treatments." (PMID 41008982, 2025). "In other words, SIRT1 is necessary to maintain the suppressive identity of MDSCs, and when it is inhibited, the balance shifts toward a more inflammatory and tumor-rejection-oriented immune response." (PMID 41425553, 2025).